PSMD12 (proteasome 26S subunit, non-ATPase 12)
Diseases named in the same sentence as PSMD12 in open-access papers:
PSMD12 is named in the same sentence as 46 diseases in open-access papers, as found by Europe PMC text mining. Sharing a sentence is not in itself a finding about the gene and the disease. The quoted sentences say what the papers report.
breast carcinoma (6 papers, 2021 to 2025). "As a proteasome subunit, PSMD12 is involved in the regulation of protein degradation, and its elevated expression inhibits apoptosis signaling pathways to maintain the survival of breast cancer cells." (PMID 40657358, 2025). "In this study, by integrating CRISPR-CAS9 functional genomics (DEPMAP database) and TCGA multi-omics data, seven key genes (CDK7, CLTC, COPB2, CRNKL1, GSPT1, NSF and PSMD12) that are closely related to the proliferation and prognosis of breast cancer were systematically identified." (PMID 40657358, 2025). "We also confirmed via qRT-PCR that proteasome subunit genes, such as PSMB7 and PSMD12, which are induced by NRF1 when the proteasome is inhibited, had attenuated expression in the NRF1-knockdown breast cancer cell lines." (PMID 37739987, 2023). "The levels of PSMD1, PSMD2, PSMD3, PSMD7, PSMD10, PSMD12, and PSMD14 are high in breast cancer tissue compared to normal tissues." (PMID 36934426, 2023).
glioma (5 papers, 2017 to 2023). A benign or malignant brain and spinal cord tumor that arises from glial cells (astrocytes, oligodendrocytes, ependymal cells). "PSMD12 enhanced the proliferation and invasion of glioma cells through Akt signaling-mediated Nrf2 expression, and PSMD12 was considered to be a key regulator of glioma development and progression." (PMID 37349676, 2023). "In addition, PSMD12 expression is reportedly upregulated in glioma tissues compared with normal brain tissues and positively correlated with glioma grade." (PMID 34868920, 2021). "High levels of PSMD12 enhanced both the proliferation and invasion of BRCA and gliomas, one of the fastest-growing and most aggressive brain neoplasms, by upregulating nuclear factor erythroid 2-related factor 2 (Nrf2)." (PMID 34839279, 2021). "This study found the prognostic predictive values of the hypoxia-related genes PSMB10, PSMD12, UBB, PSMA5, and PSMB6 for glioma and provided ideas and entry points for the progress of hypoxia-related glioma." (PMID 34868920, 2021). "The results showed that PSMB6, PSMA5, UBB, and PSMD12 were significantly downregulated, and PSMB10 was significantly upregulated in gliomas." (PMID 34868920, 2021). "The results showed that PSMB6, PSMA5, UBB, and PSMD12 were highly expressed in the glioma tissues, while PSMB10 was lowly expressed in the glioma tissues compared with the normal tissues." (PMID 34868920, 2021). "Notably, PSMB10, PSMD12, UBB, PSMA5, and PSMB6 were found to be independent prognostic predictive markers for glioma." (PMID 34868920, 2021). "Univariate and multifactorial COX regression analyses were used to determine that PSMB10, PSMD12, UBB, PSMA5, and PSMB6 may be independent prognostic factors for gliomas." (PMID 34868920, 2021). "PSMB10, PSMD12, UBB, PSMA5, and PSMB6 were found to be independent predictors of glioma prognosis." (PMID 34868920, 2021). "In addition, PSMB6, PSMA5, UBB, and PSMD12 were lowly expressed, while PSMB10 was highly expressed, in the TCGA and GTEx integrated glioma samples and normal samples, which were verified through protein expression levels in the Human Protein Atlas database." (PMID 34868920, 2021). "In this study, our objective was to analyse whether SMB6, PSMD9, UBB, PSMD12, PSMB10, PSMA5, and PSMD14 are independent prognostic factors for glioma." (PMID 34868920, 2021).
Intellectual disability (4 papers, 2018 to 2023). "A mutation in PSMD12 has been identified in a multiplex family with intellectual disability." (PMID 37016705, 2023). "For instance, our work recently revealed that subjects with genomic alterations in the PSMD12 gene encoding the PSMD12 (i.e., Rpn5) subunit of the 19S regulatory particle do not suffer from CANDLE/PRAAS but syndromic intellectual disability (SID)." (PMID 31827472, 2019).
Stankiewicz-Isidor syndrome (4 papers, 2021). "Variants in PSMD12 cause Stankiewicz-Isidor syndrome, sometimes associated with congenital heart defects, and variant carrier 06-095 has a diagnosis of APAH-CHD." (PMID 33971972, 2021). "The opportunity to perform trio WES at the age of nine months resulted in the confirmation of a Stankiewicz-Isidor syndrome, a rare condition due to pathologic monoallelic variants in the PSMD12 gene, first described in 2017." (PMID 34772435, 2021). "Notably however, de novo mutations in an interacting subunit, Rpn5/PSMD12, causes Stankiewicz-Isidor syndrome; a recently discovered neurodevelopmental disorder with a strong congenital cardiac malformation component." (PMID 34906219, 2021).
hepatocellular carcinoma (3 papers, 2017 to 2025). A malignant tumor that arises from hepatocytes. "Upregulation of PSMA6, PSMB4, PSMC2 and PSMD12 was also observed in hepatocellular carcinomas in p21-HBx transgenic mice." (PMID 27966459, 2017).
autism (2 papers, 2020 to 2021). Persistent deficits in social interaction and communication and interaction as well as a markedly restricted repertoire of activity and interest as well as repetitive patterns of behavior. "PSMD12 variants have been also associated with a large family with ID and autism and one simplex case with periventricular nodular heterotopia." (PMID 32500975, 2020). "PSMD12 was found in foetuses with neurodevelopmental disorders characteristic of autism and craniofacial anomalies, clubfoot, and syndactyly." (PMID 34868920, 2021).
liver cancer (2 papers, 2022 to 2025). An epithelial or non-epithelial malignant neoplasm that arises from the liver. "Furthermore, multivariate Cox regression analysis indicated that PSMD12 expression was an independent risk factor for the prognosis of liver cancer patients (HR = 1.493, 95% CI: 1.018–2.191, P = .04)." (PMID 36137220, 2022). "Studies have found that PSMD12 promotes the development of liver cancer by upregulating KIF15 and promoting the activation of the MEK-ERK pathway." (PMID 41444773, 2025). "In summary, our study shows that in liver cancer cells, PSMD12 promotes the expression of KIF15, thereby regulating the activation of MEK-ERK to promote malignant tumor progression." (PMID 36137220, 2022). "Subsequently, we performed IHC to detect the expression of KIF15 and PSMD12 in liver cancer tissues." (PMID 36137220, 2022). "To explore the functions of PSMD12 in liver cancer, we analyzed the expression level of PSMD12 in tumor tissues and normal liver tissues in TCGA database." (PMID 36137220, 2022). "The relationship between the expression of PSMD12 mRNA and the prognosis of liver cancer patients was analyzed through the Kaplan–Meier plotter online database." (PMID 36137220, 2022). "We observed that knocking down PSMD12 in liver cancer cells can inhibit tumor cell proliferation, migration and invasion." (PMID 36137220, 2022). "The result was consistent with TCGA data analysis, and KIF15 expression was highly increased in liver cancer tissues with high levels of PSMD12." (PMID 36137220, 2022). "We performed GSEA based on TCGA to further explore the regulatory mechanism of PSMD12 on the proliferation and invasion of liver cancer." (PMID 36137220, 2022). "We found that PSMD12 is a tumor-promoting gene in liver cancer, and its high expression is closely related to the poor prognosis of patients." (PMID 36137220, 2022). "In-depth study of the specific mechanism of PSMD12 in liver cancer can provide a target for the treatment of liver cancer and provide a basis for the development of new drugs." (PMID 36137220, 2022). "In addition, the expression of PSMD12 was detected in normal liver tissues and liver cancer tissues." (PMID 36137220, 2022). "To test our hypothesis, we conducted a rescue experiment and observed that knockdown of KIF15 in PSMD12-overexpressing liver cancer cells can restore the progression of tumor malignancy and the activation of the MEK-ERK signaling pathway induced by PSMD12." (PMID 36137220, 2022). "In addition, we found that PSMD12 can promote the activation of the MEK-ERK pathway in liver cancer cells by upregulating the expression of KIF15, which is a member of the kinesin family, thereby promoting the malignant progression of tumors." (PMID 36137220, 2022). "In addition, knockdown of PSMD12 in liver cancer cells results in a decrease in KIF15 expression, while overexpression of PSMD12 increases the protein level of KIF15." (PMID 36137220, 2022).
pancreatic cancer (2 papers, 2024 to 2025). "Additionally, PSMD12 interacts with CDKN3 and facilitates the progression of pancreatic cancer." (PMID 41444773, 2025).
bladder cancer (1 paper, 2017). "These included proteins previously associated with bladder cancer and also additional novel such as PGRMC1, FUCA1, BROX and PSMD12, which were further confirmed by immunohistochemistry." (PMID 29050215, 2017).
breast tumor (1 paper, 2021). "Immunohistochemical (IHC) images revealed dense distributions of PSMD2 and PSMD4, while the other PSMDs, including PSMD1, PSMD2, PSMD3, PSMD7, PSMD12, and PSMD14, were moderately distributed in breast tumor samples." (PMID 34839279, 2021).
colon cancer (1 paper, 2025). "However, Amino Acid Metabolism Reprogramming found PSMD12 as a protective factor in colon cancer, aligning with our findings." (PMID 41444773, 2025).
influenza (1 paper, 2022). An acute viral infection of the respiratory tract, occurring in isolated cases, in epidemics, or in pandemics; it is caused by serologically different strains of viruses (influenzaviruses) designated A, B, and C, has a 3-day incubation period, and usually lasts for 3 to 10 days. "Among them, PSMD12, a 26S proteasome regulatory subunit, was shown to interact with influenza M1, acting as a positive host factor in IAV replication in avian and human cells." (PMID 35861516, 2022).
ischemia (1 paper, 2025). A hypoperfusion of the BLOOD through an organ or tissue caused by a PATHOLOGIC CONSTRICTION or obstruction of its BLOOD VESSELS, or an absence of BLOOD CIRCULATION. "Research suggests that RPS27A promotes the expression of inflammatory factors in microglial cells by regulating the PSMD12/NF-κB signaling axis, which facilitates immune cell infiltration into brain tissue and exacerbates brain damage in ischemia/reperfusion models." (PMID 40409241, 2025).
lung adenocarcinoma (1 paper, 2021). A carcinoma that arises from the lung and is characterized by the presence of malignant glandular epithelial cells. "Seven other 26S/20S proteasome subunits were isolated (q < 0.05; PSMD12, PSMB4, PSMA6, PSMB6, PSMC1, PSMD3, and PSMB3), illuminating the importance of the 26/20S proteasome integrity in lung adenocarcinoma genome maintenance." (PMID 34070461, 2021).
microcephaly (1 paper, 2024). A congenital or acquired developmental disorder in which the circumference of the head is smaller than normal for the person's age and sex. "Proteasome subunit mutations in PSMB1, PSMC3, and PSMD12 are associated with craniofacial dysmorphisms in humans, including microcephaly, semicircular canal malformations, and retrognathia and microretrognathia, respectively." (PMID 39171526, 2024).
renal cell carcinoma (1 paper, 2023). "These 27 CTTs including 8 genes CTNNA1, PSMB6, PSMD12, SESN2, SLC22A2, UBE2J2, and NAE1 appeared in the SL pairs of renal cell carcinoma in previous literature studies." (PMID 38074121, 2023).
spinocerebellar ataxia (1 paper, 2025). "Among the most significantly enriched proteins within the spinocerebellar ataxia pathway were proteasome 26S subunit (PSMD1, PSMD7, PSMD12, PSMD13), specifically the non-ATPase regulatory components, which are central to the degradation of ubiquitinated proteins." (PMID 41441337, 2025).
cancer (7 papers, 2017 to 2025). A tumor composed of atypical neoplastic, often pleomorphic cells that invade other tissues. "The correlation between PSMD12 expression and patient prognosis in various cancers was evaluated using the log-rank test." (PMID 40534847, 2025). "Although, numerous inhibitors targeting the proteolytic activity of 26S proteasome complex have been investigated as potential anti-tumor agents, the relevance of PSMD12 in cancer has not been investigated yet." (PMID 29050215, 2017).
neurodevelopmental disorder (6 papers, 2020 to 2024). A behavioral and cognitive disorder with onset during the developmental period that involves impaired or aberrant development of intellectual, motor, or social functions. "Previous published work has shown that nonsense or missense variants of proteasome subunits PSMB1, PSMC3, and PSMD12 are associated with neurodevelopmental disorders." (PMID 38776958, 2024). "A missense variant in TEKT4 was discovered in a family with PSMD12 haploinsufficiency, a neurodevelopmental disorder with autistic features." (PMID 37872607, 2023). "More recently, mutations in the subunits of the 19S (the major 20S regulator) RPN5 (PSMD12) or RPT5 (PSMC3) have been linked to neurodevelopmental disorders." (PMID 36980185, 2023). "Furthermore, mutations in genes encoding proteasome subunits result in neurodevelopmental disorders, as exemplified by variants of genes encoding the 20S CP subunit PSMB1 (β1) and the 19S RP subunits PSMC3 and PSMD12." (PMID 38776958, 2024).
tumor (6 papers, 2017 to 2025). "In vivo, experiments showed that CDK1 restoration alleviated the tumor growth suppression caused by PSMD12 knockdown, with IHC staining of tumor tissues from nude mice further corroborating these results." (PMID 40534847, 2025). "Results showed a significant increase in PSMD12 expression in tumor tissues compared to non-tumor tissues in TCGA, GSE121248, GSE14520, and ICGC." (PMID 40534847, 2025). "Recent studies have demonstrated elevated PSMD12 expression in various tumor types, correlating with poor clinical outcomes." (PMID 40534847, 2025). "Here, through bioinformatics analysis, immunohistochemical staining, cellular experiments and the construction of an animal model, we first found that PSMD12 is an oncogene in HCC that can promote the progression of the malignant phenotype of tumor cells." (PMID 36137220, 2022). "In vitro experiments suggested that PSMD12 knockdown attenuated tumor cell growth, invasion and migration." (PMID 36137220, 2022). "We found that the expression of PSMD12 was significantly increased in the tumor tissues compared with normal tissues." (PMID 36137220, 2022). "However, in contrast to normal epithelial tissues, the expression of FBXL5, PSMB2, and PSMD12 was markedly decreased in tumor epithelial cells." (PMID 41444773, 2025). "Moreover, IHC analysis showed that knockdown of PSMD12 decreased the expression of KI67 in tumor tissue, and the p-ERK and KIF15 index of the PSMD12 knockdown group was also lower than that of the NC group, which is consistent with our previous study." (PMID 36137220, 2022). "KIF15 knockdown impaired tumor progression and tumor-promoting effect of PSMD12." (PMID 36137220, 2022). "The results showed that the weight and size of xenografts in the PSMD12 knockdown group were significantly smaller than those in the NC group, indicating that PSMD12 could promote the growth of tumor cells." (PMID 36137220, 2022). "Moreover, the expression of PSMD12 was positively correlated with the higher-grade tumor stage of the patient, and the results were statistically significant." (PMID 36137220, 2022). "The ERK inhibitor could alleviate the tumor-promoting effect in PSMD12-overexpression cells." (PMID 36137220, 2022). "The mRNA expression of PSMD12 was closely related to MAPK1 and MAP2K1, which indicates that PSMD12 is most likely to regulate tumor progression by the ERK pathway." (PMID 36137220, 2022). "In conclusion, PSMD12 could activated MEK-ERK pathway via KIF15 upregulation, thereby promoting tumor progression." (PMID 36137220, 2022). "In addition, we found that PSMD12 can activate the MEK-ERK signaling pathway by upregulating the expression of KIF15, which is the molecular mechanism by which PSMD12 promotes the malignant progression of tumor cells." (PMID 36137220, 2022). "We found that PSMD12 expression was obviously higher in tumor tissues than in normal tissues." (PMID 36137220, 2022).
neurodegenerative disease (2 papers, 2022 to 2023). A disorder of the central nervous system characterized by gradual and progressive loss of neural tissue and neurologic function. "Considering the KEGG pathways, the most enriched terms are related to neurodegenerative diseases with the involvement of the same hubs Psmd1 and Psmd12." (PMID 37355705, 2023).
PSMD12 also shares sentences with these, for which no sentence is quoted: infection (3 papers); bacterial infection (1); brain malformations (1); brain neoplasm (1); cardiac hypertrophy (1); cataract (1); Cerebral ischemia (1); cervical cancer (1); colorectal cancer (1); congenital heart defects (1); deafness (1); dilated cardiomyopathy (1); Epstein-Barr virus infection (1); gram-negative bacterial infections (1); gram-positive bacterial infections (1); lentivirus infection (1); mastitis (1); Neurodevelopmental delay (1); ovarian serous carcinoma (1); Parkinson disease (1); periventricular nodular heterotopia (1); prostate carcinoma (1); Salmonella Infections (1); serous ovarian cancer (1); syndactyly (1).